PAPPA (pappalysin 1)
Diseases named in the same sentence as PAPPA in open-access papers (continued):
Sharing a sentence is not in itself a finding about the gene and the disease.
melanoma (continued). "To evaluate the previously unknown role of PAPPA in melanoma, we utilised an embryonic chicken transplantation model that is gaining traction for melanoma tumor invasion studies in vivo." (PMID 25940796, 2015). "Notably, inhibition of PAPPA significantly reduced invasion and migration of melanoma cells in vitro and in vivo within the embryonic chicken neural tube." (PMID 25940796, 2015). "Notably, IGFBP-4, the primary substrate of PAPPA was upregulated in mesenchymal-like melanoma cells." (PMID 25940796, 2015). "To determine whether elevated PAPPA in maternal circulation during pregnancy can accelerate melanoma progression, we initially examined the level of secreted PAPPA in pregnant sera." (PMID 25940796, 2015). "PAPPA-enriched pregnancy serum treatment enhanced melanoma motility in vitro." (PMID 25940796, 2015). "We found differential expression of PAPPA and have now extended those investigations to show that PAPPA expression was associated with mesenchymal-like but not epithelial-like melanoma cell lines." (PMID 25940796, 2015). "We next sought to investigate whether reduced PAPPA expression would lead to a reduction in melanoma cell migration and we found that high PAPPA-expressing cell lines exhibited statistically significant positive correlation with migration when compared to low PAPPA expressing lines." (PMID 25940796, 2015). "Interestingly, PAPPA expression has been detected in developing neural crest cells and since melanocytes are embryologically derived from neural crest, it is likely that the environmental signals in this model are pertinent to melanoma cell motility." (PMID 25940796, 2015). "qRT-PCR revealed PAPPA mRNA expression only in mesenchymal-like melanoma cell lines and not those with an epithelial-like phenotype." (PMID 25940796, 2015). "In LM-MEL-62, an epithelial-like melanoma cell line with no inherent PAPPA production, co-culture with PS lead to change in morphology with induction of cell spreading and invasive protrusions as compared to control sera." (PMID 25940796, 2015). "Next, melanoma cells transfected with PAPPA siRNA or a non-targeting control were cultured as hanging drop for 24 hours and then introduced into the trunk neural tube of a developing chick embryo." (PMID 25940796, 2015). "As PAPPA is a known modulator of IGF bioavailability, we tested whether bioactive, non IGFBP-bound IGF1 could restore the migratory ability of melanoma cells after silencing PAPPA gene expression." (PMID 25940796, 2015). "As expected, higher amount of PAPPA was detected by ELISA in thirteen from pregnant women (PS) sera collected in third trimester of gestation compared with non-pregnant control serum and melanoma cell lines." (PMID 25940796, 2015). "Although we demonstrated induction of a mesenchymal phenotype by IGF1 and enrichment of PAPPA in mesenchymal-like melanoma cells, we did not exhaustively study the role of PAPPA in modulating alternative signalling pathways such as TGF-β, another potent inducer of EMT." (PMID 25940796, 2015). "Based on the multi-domain structure of PAPPA, it is conceivable that there may be other non-proteolytic mechanisms involved in promoting the various functions of PAPPA in melanoma." (PMID 25940796, 2015). "However, the role of PAPPA in melanoma progression has not previously been described." (PMID 25940796, 2015).
Sepsis (2 papers, 2013 to 2015). Sepsis is defined as life-threatening organ dysfunction caused by a dysregulated host response to infection. "The serum pappalysin-1 concentration frequently increases in patients with severe sepsis and appears to be associated with sepsis-related myocardial dysfunction." (PMID 25628020, 2015).
thyroid nodule (2 papers, 2022). A small circumscribed mass in the THYROID GLAND that can be of neoplastic growth or non-neoplastic abnormality. "Furthermore, we investigated the potential diagnostic role of PAPPA to discriminate benign and malignant thyroid nodules in cytological material obtained after fine-needle aspiration." (PMID 34350538, 2022). "In this study, we examined whether PAPPA expression could represent a promising new screening test in the management of indeterminate thyroid nodules." (PMID 35563038, 2022).
Alzheimer disease (1 paper, 2017). A progressive, neurodegenerative disease characterized by loss of function and death of nerve cells in several areas of the brain leading to loss of cognitive function such as memory and language. "by using the keywords pappalysin-1/Pregnancy-associated plasma protein-A (PAPP-A) and Alzheimer’s disease revealed only one publication that associates PAPP-A with depressive symptoms." (PMID 29088293, 2017).
female infertility (1 paper, 2017). Diminished or absent ability of a female to achieve conception. "Therefore, we suggest that PAPPA could be considered a potential clinical biomarker to diagnose female infertility and a therapeutic target to improve embryo and endometrium dysfunction in implantation." (PMID 28706275, 2017).
metastatic melanoma (1 paper, 2015). A melanoma that has spread from its primary site to another anatomic site. "Cytoplasmic and membranous PAPPA expression was detected in 73% of metastatic melanoma patient tumors." (PMID 25940796, 2015).
migraine (1 paper, 2023). "Furthermore, we integrated the plasma proteomic dataset with migraine GWAS data for another PWAS, identifying five more genes (MRVI1, PAPPA, B3GNT8, XCL2, and EPHA10) as potential risk genes." (PMID 37592229, 2023).
osteoarthritis (1 paper, 2024). A noninflammatory degenerative joint disease occurring chiefly in older persons, characterized by degeneration of the articular cartilage, hypertrophy of bone at the margins and changes in the synovial membrane. "A study conducted in dogs treated with protease inhibitors showed that increased levels of intact IGFBP5 result in an improvement in joint architecture during development of osteoarthritis, indicating a negative role of increased levels of PAPPA." (PMID 38479789, 2024).
pancreatic cancer (1 paper, 2015). "Moreover, LOX was 1 out of only 5 probe sets that overlapped between the Glasgow cohort and the Collisson signatures of poor prognosis in pancreatic cancer (the others being S100A2, TWIST, NT5E and PAPPA)." (PMID 26077591, 2015).
thyroid (1 paper, 2022). "Only one study reports increased PAPPA mRNA levels in thyroid malignancies using online gene profiling data." (PMID 34350538, 2022). "When applied on thyroid cytologies, PAPPA expression was able to discriminate benign from malignant nodules contributing to pre-surgical classification of the nodules." (PMID 34350538, 2022).
thyroid tumor (1 paper, 2022). A benign or malignant neoplasm affecting the thyroid gland. "Since the results on thyroid tumor were robust and reproducible also at protein level, we investigated the possibility to analyze PAPPA expression in cytological samples as diagnostic marker to discriminate benign from malignant nodules." (PMID 34350538, 2022).
tumor (63 papers, 2008 to 2026). "Using integrated public datasets, we systematically examined PAPPA expression, prognostic relevance, cellular localization, and stromal associations across multiple tumor types." (PMID 41892220, 2026). "rs10982853 was associated with differential expression in PAPPA in eQTL analysis using tumor tissues (p = 0.028)." (PMID 38664626, 2024). "Consistent with the role of PAPPA secretion in tumor growth, PAPPA knockdown in A549 resulted in a significant reduction in tumor growth when the cells were implanted in immune-deficient mice." (PMID 23152806, 2012). "On the contrary, mice bearing a null mutation of the PAPPA gene live longer and show less incidence of tumor formation during their lifetime." (PMID 23152806, 2012). "Several lines of evidences indicate that PAPPA is implicated in tumor formation." (PMID 23152806, 2012). "It was determined that circ-PAPPA expression was associated with TNM stage, lymphatic metastasis, tumor size, and distant metastasis; and circ-PAPPA expression had a negative correlation with patients’ survival." (PMID 39951875, 2025). "It has been demonstrated that MGP, COL8A2, and PAPPA are effective immunological checkpoints that mediate tumor immunosuppression." (PMID 37777759, 2023). "Results confirmed higher levels of PAPPA expression in fibroblasts compared to tumor cells, although epithelial PAPPA transcripts were also seen in some ILC tumors." (PMID 35205651, 2022). "Consistently, in our study, we revealed the upregulation of PAPPA in the PABC tumor tissues and serum." (PMID 34974815, 2022). "Although PAPPA has been discovered for its vital role in pregnancy, this protein acts as an oncogene, promoting tumor cell proliferation, invasion, and metastasis." (PMID 31900413, 2020). "They identified 158 genes that dysregulated in tumor tissues; these genes are related to proteolysis and cell adhesion, including PAPPA." (PMID 32685491, 2020). "Application of our modeling strategy unmasked PAPPA as a novel paracrine factor that shapes the tumor phenotype via activating the NFκB pathway." (PMID 26020769, 2015). "Emerging evidence suggests that disrupting the regulation of IGF1 availability by aberrant expression of PAPPA can impact tumor biology." (PMID 25940796, 2015). "In liver cancer patients, higher levels of PAPPA protein indicate a more progressed tumor stage, confirming its clinical relevance." (PMID 26020769, 2015). "Immunohistochemical staining of cell line matched patient derived tumor biopsies revealed positive cytoplasmic and membranous staining for PAPPA." (PMID 25940796, 2015). "The tumor promoting activity of PAPPA appears to be mediated mainly through augmentation of the IGF signaling pathway as indicated by notable increases in downstream Akt kinase phosphorylation in tumor samples." (PMID 23152806, 2012). "Our study confirmed the role of PAPPA in lung tumor growth and further defined that it is the secreted PAPPA from tumor cells that is critical for its tumor promotion activities." (PMID 23152806, 2012). "Taken together, these results suggest that secreted form of PAPPA is critical for its tumor promotion activity in vivo." (PMID 23152806, 2012). "Our results indicate that deregulation of PAPPA expression and secretion is one of the driving forces for tumor progression." (PMID 23152806, 2012). "We found that the increased PAPPA secretion in tumor tissues is accompanied predominantly by activation of IGF1R-Akt signaling pathway." (PMID 23152806, 2012). "The serum level of PAPPA from tumor bearing mice at the end of experiment was measured in both the H1299/PAPPAov group and the respective control group." (PMID 23152806, 2012). "The role of PAPPA in tumor progression defined in this report revealed a new potential target related to targeted therapy of the IGF signaling pathway." (PMID 23152806, 2012). "Xenograft models proved to be more appropriate to evaluate the effect of PAPPA secretion on tumor growth." (PMID 23152806, 2012).
tumor (continued). "Down-regulation of PAPPA expression and secretion by RNAi knockdown decreases tumor growth after implanted in vivo." (PMID 23152806, 2012). "As expected, tumors generated from A549 cell line with PAPPA knockdown (A549/PAPPAkd) exhibited significant reduction in tumor growth when compared to A549 control cell line." (PMID 23152806, 2012). "TJP1 (ZO-1) and TJP2 (ZO-2) proteins were also expressed by the majority of progenitor and stem cells from tumor cell cultures, whereas only a minority of the total cell population expressed PAPPA." (PMID 18492237, 2008). "Hence, upregulating the gene by blocking the IGF complex favors tumor suppression and is also a sign of activity accelerating proteolysis of two proteinase genes (PAPPA and MMP2)." (PMID 39854135, 2025). "High expression of FOSB+, NEAT1+, or XIST+ tumor cell-associated genes such as FSTL3, VTN, PAPPA, CCN1, RRAD, and GPRIN3 may predict poor survival in patients with LUSC, suggesting that these genes act as prognosis biomarkers." (PMID 37430270, 2023). "PAPPA was the most enriched gene in the stroma compared to the tumor epithelial compartment in ILC." (PMID 35205651, 2022). "We also stained the cell proliferation marker Ki-67 and PAPPA in the tumor sections." (PMID 34974815, 2022). "Therefore, PAPPA appears as a better therapeutic target for HCC with more tumor specificity and less risks of side effects as compared to other IGF1 axis components." (PMID 26020769, 2015). "We unmasked PAPPA as a novel stroma secreted factor impacting the tumor phenotype." (PMID 26020769, 2015). "Given the fact that knockdown of PAPPA affected cell functions including cell migration in vitro and tumor development in vivo, we propose that it might be used a novel therapeutic target for the treatment of MPM." (PMID 23896451, 2013). "Finally, we used an orthotopic xenograft mouse model of MPM to evaluate the efficacy of PAPPA silencing on tumor development and progression in vivo." (PMID 23896451, 2013). "Finally, we used a mouse orthotopic xenograft model to investigate the roles of PAPPA in MPM tumor progression in vivo." (PMID 23896451, 2013). "Increased tumor growth in PAPPA secreting cell lines could result from the enhanced IGF signaling caused by degradation of IGFBP4 and thus increases in the bioavailability of IGFs." (PMID 23152806, 2012). "We decided to examine the role of PAPPA in tumor growth in vivo in xenograft models." (PMID 23152806, 2012). "Taken together, these results suggested that the ability of cancer cells to secret PAPPA rather than cellular PAPPA content is associated with tumor growth and progression." (PMID 23152806, 2012). "In addition, increased cell proliferation and reduced apoptosis were observed in tumor tissues over-expressing PAPPA." (PMID 23152806, 2012). "Our results suggest that secreted PAPPA in cancer cells could promote tumor development through potentiating the IGF signaling pathway." (PMID 23152806, 2012). "Furthermore, PAPPA also inhibited the expression of interferon responsive genes and of HLA molecules required for antigen presentation, thus reducing the immunogenicity of tumor cells." (PMID 36345344, 2022). "In tumor tissues, four protective genes (JAK2, IL2RG, EEF1E1, and UBB) showed relatively low expression in the high‐risk group; in contrast, the expression of four risk genes (EPS8, FOXO1, STAT5A, and PAPPA) was more highly in the high‐risk group than that in the low‐risk group." (PMID 34825509, 2021). "Therefore, PAPPA might serve as a better therapeutic target for MPM with more tumor specificity and less risks of side effects as compared to IGF-1 axis components as targets." (PMID 23896451, 2013). "Even though H1299 and H1792 might have different genetic makeup that may render them reliant on different signaling transduction pathways for growth, it appears that the activity of PAPPA in the promotion of tumor growth is tied to the capability of cells to secret functional PAPPA." (PMID 23152806, 2012).
tumor (continued). "Collectively, these findings establish PAPPA as an independent prognostic factor across most cancers, while its expression frequently coincides with high CAF infiltration in select tumor types, highlighting the need for further investigation." (PMID 41892220, 2026). "PAPPA differs from BCL7C and EML2; its overexpression promotes tumor growth, and it is related to IGFBP hydrolysis and activation of NF-κB, PI3K, and other pathways, which are closely related to hair follicles and wool fibers." (PMID 37894908, 2023). "PAPPA, a gene involved in IGF-1 signaling, was the most enriched in the stroma compared to the tumor epithelial compartment in ILC." (PMID 35205651, 2022). "In ILC, both PAPPA and IGF1 were significantly upregulated in the stroma compared to the epithelium (p < 0.0001), while IGF1R was found predominantly in the tumor epithelium (p < 0.05)." (PMID 35205651, 2022). "This makes PAPPA a promising therapeutic target in HCC, as tumor stromal cells are genetically more stable than cancer cells, which renders them less likely to evade therapy." (PMID 26020769, 2015). "Taken together, transfection of PAPPA shRNA in MPM cells confirmed the important role of PAPPA in cell migration, invasion and proliferation, further revealed its crucial role in MPM tumor development and progression in vivo." (PMID 23896451, 2013). "However, we found that both PAPPA and IGF1 were predominantly expressed in the stroma of ILC, while IGF1R was expressed within the tumor epithelium." (PMID 35205651, 2022). "Nevertheless, miR-500a-3p may serve as a tumor suppressor through inhibiting LIF and PAPPA, and TDP-43 might contribute to inhibiting cancer progression by modulating miR-500a-3p target genes." (PMID 28952053, 2018). "Our studies reveal a fourth resistance mechanism, in which cabozantinib induces the secretion of a spectrum of proteins, e.g. PAPPA and IGFBP2 that are known to increase tumorigenic properties of PCa cells, from osteoblasts to increase the survival and migration of tumor cells." (PMID 29088840, 2017). "Even though most of the studies on PAPPA so far suggested its tumor-promoting role is largely IGF-1-dependent, anti-PAPPA therapy might provide therapeutic effects beyond the inhibition of the IGF-1/IGF-1R signaling axis." (PMID 23896451, 2013). "Over-expression of PAPPA in H1299 has no notable effect on cell growth in vitro but significantly increases in the tumor growth in vivo as a xenograft model." (PMID 23152806, 2012). "In contrast, a cell line over-expressing PAPPA without secretion exhibits reduction of tumor growth both in vitro and in vivo." (PMID 23152806, 2012). "Furthermore, siRNA- or shRNA-mediated silencing of PAPPA led to inhibition of migration and proliferation of MPM cells and inhibited tumor growth in mouse orthotopic xenograft models, suggesting that pappalysin 1 could represent a potential therapeutic target." (PMID 32882916, 2020). "A cell line over-expressing PAPPA accompanied with secretion shows no notable changes in proliferation under cell culture conditions in vitro, but displays significantly augmentation of tumor growth in vivo in a xenograft model." (PMID 23152806, 2012).